CCK (cholecystokinin)
Diseases named in the same sentence as CCK in open-access papers (continued):
Sharing a sentence is not in itself a finding about the gene and the disease.
Anxiety (continued). "As various mental disorders, including anxiety, depression, and PTSD, are highly correlated with hyperactivation and dysfunction of the amygdala and the fear memory circuitry, our finding supports CCK and its receptors as potential new targets for future therapeutic applications for these disorders." (PMID 34779397, 2021). "The increased CCK-positive neurons in the amygdala at the prediabetic and early stage of type 2 diabetes in OLETF rats might be involved in specific anxiety-related phenotypes in the open field test found at the stages, such as decreased locomotion in the center zone." (PMID 34506507, 2021). "If so, the lack of intracellular processing of CCK-5 to CCK-4 might make sense as a way to prevent severe panic attacks and anxiety." (PMID 34577128, 2021). "Further support for our hypothesis that CCK plays a critical role in behavior, are studies showing that blockade of CCK receptors suppresses conditioned fear, and deletion of the CCKB receptor gene reduces anxiety-like behavior." (PMID 31980587, 2020). "Cholecystokinin (CCK): A study by Brawman-Mintzer reported that intravenous pentagastrin, a CCK-B receptor agonist, induced higher rates of panic attacks in patients with GAD compared with the controls, suggesting that CCK hypersensitivity could play a role in the pathophysiology of this disorder." (PMID 32824625, 2020). "Thus, observed contextual episodic and spatial working memory impairments observed in SDV and CCK-SAP rats are unlikely to be secondary to effects on anxiety-like behavior." (PMID 29872139, 2018). "However, CCK injections in the mPFC, amygdala, hippocampus, and cerebral ventricle reportedly increased anxiety-like behavior via the activation of the CCK-2 receptor, whereas knockout of CCK-1 receptor did not generate anxiety-like behavior." (PMID 34506507, 2021). "Additionally, lower concentrations of Cholecystokinin-8 (CCK-8) in CSF and in peripheral lymphocytes have been reported in PDA patients but not in healthy subjects, showing abnormalities in the entire CCK system (CCK-4 and CCK-8) and underpinning the pathophysiology of anxiety and panic disorder." (PMID 32824625, 2020). "Finally, we used a novel open field test to confirm that the differences observed in the extinction retrieval were due to the manipulation of the BA CCK+ cells participating in fear circuits, and not to a different locomotor or anxiety level within the different groups." (PMID 31636080, 2019). "The VH, which has been described as a player in the anxiety network both in rodents and humans, has not been associated with NPS actions to date, although this limbic region is well known as a target of other neuropeptides like oxytocin, arginine vasopressin, NPY and cholecystokinin (CCK)." (PMID 23555930, 2013). "Results showed that clozapine-N-oxide (CNO)-mediated activation of CCK-GABA neurons did not alter open field (OF) or tail suspension (TS) performance and only slightly increased anxiety in the elevated plus maze (EPM)." (PMID 30834305, 2019). "In female CCK-SAP rats, which showed no changes in anxiety-like behavior compared with control rats, the extent of gene modulation in the CeA was more limited than in males (13 vs. 64 differentially expressed genes) but still biased toward genes known to affect anxiety (p = .021)." (PMID 35965105, 2022).
pancreatitis (56 papers, 2009 to 2026). Inflammation of the pancreas. "In CCK induced pancreatitis, the high/supramaximal doses of CCK cause pancreatitis associated with the basolateral distribution of subapical F-actin, whereas physiologic CCK concentrations do not cause this." (PMID 37138671, 2023). "Previous work has demonstrated that NOD1 responses were the key factors in the development of pancreatitis, as reflected in the experimental pancreatitis caused by cholecystokinin hyperstimulation." (PMID 35811665, 2022). "It is well recognized that CCK, and its analog cerulein, cause pancreatitis by binding to the CCK1R in pancreatic acinar cells to activate trypsinogen and proinflammatory signaling pathways." (PMID 34314386, 2021). "In contrast, humans and non-human primates have very low expression of CCK-1 receptors, indicating a low risk of CCK-induced pancreatitis." (PMID 31175319, 2020). "Pancreatitis induced by cerulein, an analogue of cholecystokinin, causes premature activation of digestive enzymes and enhanced accumulation of cytokines and Ca2+ in the pancreas and, as such, it is a good model of acute pancreatitis." (PMID 31248019, 2019). "Cerulein, a cholecystokinin agonist, induces pancreatitis by causing excessive secretion of zymogen granules and subsequent autophagy or apoptosis of acinar cells." (PMID 30301227, 2018). "Ethanol causes a dose dependent sensitization of the pancreas to CCK or cerulein mediated pancreatitis." (PMID 24474939, 2013). "Furthermore, the initiating agents for causing pancreatitis (i.e., CCK, LPS, duct obstruction, or viral infection) at the doses used in the corresponding models have minimal effects on pancreatitis responses in the absence of alcohol treatments." (PMID 28988572, 2017). "The most widely used model of pancreatitis involves treatment with the cholecystokinin agonist caerulein, which induces local oxidative stress, inflammation, edema, and loss of the acinar parenchyma that is transiently replaced by a duct-like epithelium, features reminiscent of human pancreatitis." (PMID 32371554, 2020). "Blocking of the acini by both somatostatins, which decrease cholecystokinin levels, and cholecystokinin receptor, ameliorates experimental obstruction-induced pancreatitis." (PMID 40254129, 2026). "This is supported by the finding that the inhibitors of secretion, cholecystokinin antagonist and somatostatin, ameliorate pancreatitis when introduced early in experimental settings." (PMID 40254129, 2026). "The protective effects of XBJ on necrotic cell death activation of freshly isolated mouse PACs were investigated using two representative pancreatitis toxins—cholecystokinin analog cerulein and bile acid TLCS." (PMID 41471355, 2025). "To mimic pancreatitis conditions in vitro we co-incubated pancreatic macrophages and freshly isolated CCK- (Cholecystokinin) stimulated acinar cells, which act as DAMPs." (PMID 40560328, 2025). "Cae is a hormone analogous to cholecystokinin (CCK) that binds to the acinar cell-restricted CCK-A receptor, thereby inducing pancreatitis through intrahepatic activation of digestive enzyme production and cytoplasmic vacuolization." (PMID 40380027, 2025). "Caerulein is an analogof cholecystokinin and gastrin that stimulates exocrine and proteolyticsecretion in the pancreas, which consequently induces a fibroinflammatoryreaction or pancreatitis." (PMID 39337472, 2024). "Application of high doses of the CCK analog cerulein in mouse models faithfully recapitulates all stages of pancreatitis." (PMID 38557489, 2024). "Inflammatory conditions such as hereditary pancreatitis predisposes to PC development and one of the most well-known mouse pancreatitis models is induced by intraperitoneal injections of the cholecystokinin analogue caerulein." (PMID 37270580, 2023). "As an analogue of the hormone cholecystokinin, caerulein triggers rapid pancreatitis in mammals and a full rapid spontaneous recovery." (PMID 36596774, 2023).
pancreatitis (continued). "Future research testing the effects of MCT on markers of pancreatic enzyme release, including CCK, in dogs with clinical pancreatitis is needed." (PMID 37624816, 2023). "As our results from CCK- or CCK analogue-dependent experimental pancreatitis models indicate a reduction in severity in the presence of hydrophobic BAs, we were interested in the impact of BAs in conditions unrelated to CCK." (PMID 36362379, 2022). "L-arginine-induced pancreatitis is characterized by CCK-independent signaling pathways, which makes this model interesting for investigations of BA-related effects." (PMID 36362379, 2022). "One physiologically relevant animal model for alcohol-related pancreatitis is the co-exposure of cholecystokinin (CCK) analogs and alcohol." (PMID 35052788, 2022). "The co-treatment of alcohol can either reduce the threshold concentration of CCK analogs required to elicit a pancreatitis response or intensify the pathologic response of the pancreas." (PMID 35052788, 2022). "When subjected to caerulein (an agonist of cholecystokinin (CCK))-induced pancreatitis, adult mice that express endogenous levels of KRASG12V in the pancreatic acinar cell compartment developed extensive PanIN lesions and PDAC with high penetrance." (PMID 33668583, 2021). "Although initial fears of increased pancreatitis risk with GLP-1 mimetic therapy in humans has now been fully allayed, extremely high doses of CCK are employed to create experimental rodent models of pancreatic inflammation." (PMID 34054734, 2021). "CER is an ortholog of the intestinal hormone cholecystokinin, which is one of the most characterized and widely used agents in experimental animal models of pancreatitis." (PMID 33927777, 2021). "Currently, the most widely utilized experimental pancreatitis model is induced by hyperstimulation of the pancreas with cerulein, a cholecystokinin (CCK) analog, in rats and mice." (PMID 34314386, 2021). "Activation of the CCK1 receptor, a GPCR, in rodents by using cerulein, a CCK analog, is widely used in experimental pancreatitis studies." (PMID 34314386, 2021). "Pancreatitis induced by caerulein, a decapeptide that stimulate Gq-coupled growth regulatory receptors (e.g., CCK), accelerates the effects of oncogenic Kras." (PMID 34249932, 2021). "Together with our findings here, it appears that both pancreatic secretions and pancreatitis elicited by CCK/cerulein are, at least partially, mediated by the CCK receptor located on neurons." (PMID 34314386, 2021). "Cholecystokinin plays a key role in driving PDAC by promoting pancreas inflammation; cerulein, a cholecystokinin analog, is frequently used to induce experimental pancreatitis and accelerate PDAC development." (PMID 33917763, 2021). "Physiological doses of CCK-8 induce pancreatic enzyme secretions, and supramaximal doses of CCK-8 cause inflammation and cell deaths, which are features of human pancreatitis." (PMID 31963306, 2020). "Among several different in vivo experimental models of AP that exhibit the same pathophysiological development of human pancreatitis, the use of cerulein, an analog of cholecystokinin (CCK), is one of most frequently used." (PMID 33066525, 2020). "Chronic alcohol feeding causes mild pancreatic damages in rodents but can promote more severe pancreatitis in the presence of endotoxin, smoking, or cholecystokinin." (PMID 31987928, 2020). "Cerulein, a CCK analog, induces pancreatitis, which is widely used as an experimental model of acute pancreatitis." (PMID 31248019, 2019). "To test if the ability of Arid1a suppression to accelerate Kras driven preneoplastic transformation is due to a defect in acinar regeneration, we challenged C-RIK-shArid1a or C-RIK-shRen mice with pancreatitis induced by the cholecystokinin analog caerulein." (PMID 30014851, 2018). "A large amount of free fatty acids generated in pancreatitis can promote the burden on the endoplasmic reticulum through cholecystokinin expression." (PMID 29362560, 2017).
pancreatitis (continued). "This reduction in secretion by high nicotine levels is similar to that seen in experimental models of pancreatitis, whereby stimulation of acinar cells with hyperstimulatory concentrations of CCK (10–100 nM) induces early stages of acute pancreatitis." (PMID 25938854, 2015). "Alcohol-induced pancreatitis requires other additional factors such as a viral infection, a high fat diet or submaximal postprandial dose of CCK or cerulein or cholinergic stimulation (such as by carbachol)." (PMID 25140315, 2014). "Treatment with supramaximal cholecystokinin (CCK) or its analogue cerulein induces pancreatitis in rodents, which has been studied extensively since the pathological and histological presentation of this model is similar to the early phase of AP in human." (PMID 25140315, 2014). "To investigate the potential requirement for active Notch signaling during pancreatitis-induced carcinogenesis, we administered a cholecystokinin (CCK) agonist (caerulein), which induces acute pancreatitis in mice (8 injections/day; 2 day treatment)." (PMID 25416148, 2014). "Hyperstimulation with the CCK ortholog cerulein induced zymogen activation and pancreatitis in wild type mice, whereas necrosis and cell death was significantly reduced in T−/− mice." (PMID 24474939, 2013). "It has been suggested that ethanol acts to sensitize the pancreas to the deleterious effects of other stimuli such as the physiological agonist cholecystokinin octapeptide (CCK-8), which then leads to an inflammatory response and pancreatitis." (PMID 19878551, 2009). "In a study in patients with post-ERCP pancreatitis, the cholecystokinin levels were increased substantially from pre-ERCP levels within hours, followed by a marked decrease during the first 24 hours after ERCP, possibly caused by duodenoscopy irritation and gas blowing." (PMID 40254129, 2026). "In rats, long-term alcohol consumption alone does not cause pancreatitis but does impair exocrine pancreatic function by decreasing blood and pancreatic cholecystokinin." (PMID 40254129, 2026). "Because CCK is a major physiological regulator of pancreatic acinar cell function, and is also important in pathophysiological models of pancreatitis, we subsequently concentrated our studies on CCK’s effect on activation of cofilin and the signaling cascades involved." (PMID 37138671, 2023). "In both caerulein-induced and BPDL pancreatitis, which caused an elevation of CCK, the severity of pancreatitis was decreased by hydrophobic BAs but not by the hydrophilic TUDCA." (PMID 36362379, 2022). "Experimental pancreatitis was induced in Balb/C mice by caerulein (Cae) and lipopolysaccharide (LPS) or L-arginine (L-Arg) in vivo, and pancreatic acinar cells were also used to follow cellular mechanisms during cholecystokinin (CCK) stimulation in vitro." (PMID 36059491, 2022). "This might be the reason that fermented alcoholic beverage products like maleate and succinate induce CCK release, which further could contribute to the development of pancreatitis." (PMID 31963306, 2020). "Pancreatic acini freshly prepared from rat were incubated with 25 μM CID755673 or 10 μM CRT0066101 for 2 h followed by challenging with a high dose of the pancreatic secretagogues CCK (100 nM) or CCh (200 μM) which were known to induce pancreatitis pathologies in acini in vitro." (PMID 29270134, 2017). "For example, in vitro and in vivo studies that focus on the effects of CCK on the transcription factor NF-κB, an intracellular signaling pathway involved in the inflammatory response of pancreatitis, show that alcohol treatments augment CCK-induced NF-κB activation." (PMID 28988572, 2017). "To delineate the role of IFN in pancreatitis we used a clinically relevant model involving injections of caerulein peptide that mimics the effects of cholecystokinin and induces key pathogenetic elements of acute pancreatitis including pancreatic duct obstruction and premature activation of trypsin." (PMID 24480543, 2014).
pancreatitis (continued). "Furthermore, both CCK and cerulein can be used to initiate hyperstimulation-induced pancreatitis in primary cultured acinar cells, which makes it a valuable tool for studying the pathophysiology and mechanisms of secretagogue-induced pancreatitis." (PMID 25140315, 2014). "The HLP caerulein, encoded by three genes in X. laevis, contains the same bioactive site as CCK and shares its capacity to bind vertebrate CCK receptors, thereby inducing pancreatitis, vomiting, diarrhea, hypotension, and inhibition of exploratory and feeding behavior." (PMID 23935531, 2013). "Our results support previously reported works, which propose that ethanol-induced sensitization of the pancreatic acinar cell results in pancreatitis responses with low doses of CCK-8, that by itself does not cause pancreatitis." (PMID 19878551, 2009). "This could occur because at different concentrations CCK activates numerous different signaling cascades that may be needed to interact with cofilin to produce a given effect such as pancreatitis." (PMID 37138671, 2023). "ANGPTL4 as well as cholecystokinin (CCK) or LPS, which are inducers of pancreatitis, was administrated to acinar cells, and we examined whether these factors directly affected the death of pancreatic acinar cells, leading to pancreatitis." (PMID 32638512, 2020). "For example, cholecystokinin (CCK) analogues cause pancreatitis in rodents in the absence of alcohol treatments only at doses much greater than those needed to activate known physiologic responses such as pancreatic enzyme secretion and gallbladder contraction." (PMID 28988572, 2017). "However, the role of ROS in pancreatitis may be controversial because they might be beneficial during acute pancreatitis by promoting apoptosis, since they mediate cerulein- or cholecystokinin-induced apoptosis in pancreatic acinar cells." (PMID 23028532, 2012). "Cer, a peptide analog of the hormone cholecystokinin (CCK), serves as a potent pharmacological agent for inducing experimental pancreatitis in research models." (PMID 38927047, 2024). "Supramaximal doses of cerulein, a cholecystokinin (CCK) analog, result in experimental pancreatitis." (PMID 32293245, 2020). "We induced pancreatitis in Wt1Cre;R26REYFP mice by injection of the secretagogue substance caerulein, an oligopeptide that acts similarly to cholecystokinin." (PMID 30763305, 2019). "Ethanol increases the effect of CCK on NF-κB activation via PKC pathways demonstrating the role of alcohol in sensitizing acinar cells to inflammatory responses and pancreatitis." (PMID 24474939, 2013). "The fact that our study shows that both physiologic and pathologic doses of CCK have the same effect on cofilin could be interpreted to suggest cofilin may not be involved in pancreatitis." (PMID 37138671, 2023). "Our results identified PKD as a novel early signaling triggered through CCK or cholinergic receptor to mediate NF-κB activation in acute pancreatitis and demonstrated that PKD inhibitors potently blocked NF-κB activation in in vitro and in vivo experimental pancreatitis models." (PMID 29270134, 2017).